NEK10 (NIMA related kinase 10)
Description:
Plays a role in the cellular response to UV irradiation. Mediates G2/M cell cycle arrest, MEK autoactivation and ERK1/2-signaling pathway activation in response to UV irradiation. In ciliated cells of airways, it is involved in the regulation of mucociliary transport.
Synonyms: FLJ32685; CILD44
Tractability: Small molecule: a high-quality ligand is known; it belongs to a druggable protein family. Antibody: its Gene Ontology location is reachable by antibodies, with medium confidence. PROTAC: ubiquitination databases record sites on it; a small molecule that binds it is known.
Target class: Other protein kinase NEK family; Kinase; Enzyme; Other protein kinase group; Protein Kinase
Gene: Protein-coding gene on chromosome 3 (27,106,484 to 27,369,460, reverse strand). Ensembl gene ENSG00000163491.
Subcellular location (Human Protein Atlas): Nucleoplasm; Vesicles
Gene Ontology:
Molecular function: protein kinase activity; protein serine/threonine kinase activity; ATP binding; protein serine kinase activity
Biological process: mucociliary clearance; positive regulation of MAP kinase activity; positive regulation of protein autophosphorylation; protein phosphorylation; regulation of cell cycle G2/M phase transition; regulation of ERK1 and ERK2 cascade
Cellular component: protein kinase complex; extracellular region
Genetic constraint (gnomAD): Loss-of-function variants: 51 observed, 64.59 expected, observed/expected ratio (o/e) 0.79, 90% interval 0.63 to 1. The upper end of that interval is the gene's LOEUF score, 1, which puts it in group 4 of 6, group 1 being the genes least tolerant of losing a copy. Missense variants: 657 observed, 654.9 expected, observed/expected ratio (o/e) 1, 90% interval 0.94 to 1.07. Synonymous variants: 234 observed, 238.43 expected, observed/expected ratio (o/e) 0.98, 90% interval 0.88 to 1.09.
Gene-disease validity (ClinGen):
ClinGen rates the evidence that NEK10 causes each of these diseases.
ciliary dyskinesia, primary, 44 (autosomal recessive): Definitive.
Homologues: Orthologues: chimpanzee NEK10 (99% identical), dog NEK10 (95% identical), rabbit NEK10 (93% identical), pig NEK10 (93% identical), rat Nek10 (89% identical), mouse Nek10 (89% identical), guinea pig NEK10 (89% identical), tropical clawed frog nek10 (70% identical), macaque NEK10 (62% identical), zebrafish nek10 (49% identical). Paralogues in human: NEK9 (12% identical), NEK5 (11% identical), NEK11 (11% identical), NEK8 (11% identical), NEK2 (9% identical), NEK3 (9% identical), NEK6 (9% identical), NEK7 (9% identical).
Diseases named in the same sentence as NEK10 in open-access papers:
NEK10 is named in the same sentence as 16 diseases in open-access papers, as found by Europe PMC text mining. Sharing a sentence is not in itself a finding about the gene and the disease. The quoted sentences say what the papers report.
breast carcinoma (13 papers, 2009 to 2024). "Decreased expression of “APOBEC3A” (OR 0.85; 95% CI 0.80–0.89; P = 1.51 × 10−9) and “NEK10” gene (OR 0.21; 95% CI 0.11–0.40; P = 1.69 × 10−6) were observed to be associated with the lower risk of breast cancer." (PMID 38659038, 2024). "Abnormalities with NEK10 expression or function have been associated with ciliary dysfunctions and breast cancer." (PMID 37046733, 2023). "Various studies looking for novel polymorphisms in carriers of the BRCA type 1/2 susceptibility protein (BRCA1/2) mutation revealed that NEK10 mutations were associated with breast cancer." (PMID 34834441, 2021). "For example, the Serine/threonine-protein kinase NEK10 (Tdark), which contains the gatekeeper residue Thr301, is associated with breast cancer by “weak evidence”, and expressed in liver, testis, trachea with “strong evidence”." (PMID 29122012, 2017). "The nsSNP giving the strongest signal in our study was rs10510592 (L513S) in NEK10, located within an established breast cancer susceptibility region." (PMID 24943594, 2014). "MAP3K1 and SLC4A7/NEK10 were associated only with risk of PR-positive breast cancer among BRCA2 mutation carriers." (PMID 22053997, 2011). "Knockdown of NEK10, a gene recently linked to breast cancer susceptibility gave the largest increase in luciferase signal (15 fold above plate mean)." (PMID 20020055, 2009). "Germline variation NEK10 is associated with breast cancer incidence." (PMID 35563727, 2022). "Besides, even protein-coding genes linked to breast cancer susceptibility, like NEK10 (P-value 1.6 × 10-5, overlapping with SLC4A7) or POU5F1B, were absent from the PPIN." (PMID 33735170, 2021). "Taken together, the studies described here suggest that mutations in NEK10 could be a biomarker for melanoma and breast cancer detection." (PMID 32294979, 2020). "Mutations in NEK10 are also associated with breast cancer development." (PMID 32294979, 2020). "A potential association of Nek10 and cancer was uncovered by a comprehensive genome wide association study (GWAS) involving over 37,000 breast cancer samples and 40,000 controls, which identified a strong breast cancer susceptibility locus within human chromosome 3p24 (p value = 4.1 × 10-23)." (PMID 22040655, 2011). "Nek8 is upregulated in primary human breast tumors, and the ectopic overexpression of Nek10 has been found in breast cancer." (PMID 25120679, 2014). "In contrast, rs4973768 in NEK10, which we found to be associated with volumetric percent density in the African-American cohort, has not been found to be associated with breast cancer risk in African-American women." (PMID 25881232, 2015). "Similar patterns were observed for SNPs rs3803662 in TOX3/TNRC9 and rs4973768 in SLC4A7/NEK10 in which the associations were predominantly with ER-positive breast cancer for both BRCA1 and BRCA2 mutation carriers, in line with results from studies of breast cancer in the general population." (PMID 22053997, 2011). "In fact, both SConES GS and GM selected chromosome regions related to breast cancer, like 3p24 (SLC4A7/NEK10), 5p12 (FGF10, MRPS30), 10q26 (FGFR2), and 16q12 (TOX3)." (PMID 33735170, 2021).
bronchiectasis (2 papers, 2020 to 2021). Segmental, irreversible dilation of the bronchial tree resulting in the accumulation of secretions which leads to obstruction. "Chivukula and co-workers recently showed the correlation of a loss of function mutation in the NEK10 (NIMA-related kinase 10) gene to the development of familial bronchiectasis in an autosomal recessive manner." (PMID 33572760, 2021). "In humans, NEK10 mutation causes bronchiectasis, a disorder of mucociliary transport in the airway due to defective motile cilia." (PMID 33064774, 2020). "In humans, NEK10 mutation causes bronchiectasis, an airway and mucociliary transport disorder caused by defective motile cilia." (PMID 33064774, 2020).
ciliopathies (2 papers, 2020 to 2023). "NEKL-4 is a homolog of human NEK10, a protein required for ciliogenesis and associated with ciliopathies." (PMID 33064774, 2020). "Notably, pathogenic variants in NEK10 have very recently been reported to be associated with situs solitus as well as normal nNO levels, while affecting ciliary growth, mucociliary transport, and thereby causing motile ciliopathy." (PMID 37998386, 2023).
melanoma (2 papers, 2020 to 2023). A malignant, usually aggressive tumor composed of atypical, neoplastic melanocytes. "In our study, we also showed that additional mutations in genes such as KRAS and NEK10 were likely to be seen in primary melanoma." (PMID 38003476, 2023). "In addition to NEK2, a study in the literature showed that NEK10 is also related to melanoma." (PMID 32294979, 2020).
glioma (1 paper, 2018). A benign or malignant brain and spinal cord tumor that arises from glial cells (astrocytes, oligodendrocytes, ependymal cells). "High levels of CHIP staining in malignant tumors were linked to low levels of NEK10, in both prostate and glioma tissues." (PMID 29581457, 2018).
microcephaly (1 paper, 2018). A congenital or acquired developmental disorder in which the circumference of the head is smaller than normal for the person's age and sex. "Defects generated by NEK10 downregulation included reduction of trunk size, microphthalmia, microcephaly, cardiovascular abnormalities, and pericardial edema, supporting a major role of this kinase in ciliary processes underlying vertebrate development." (PMID 29581457, 2018).
tumor (8 papers, 2011 to 2026). "Conversely, accumulation of CHIP in malignant tumor lesions was linked to low levels of NEK10 and reduced numbers of ciliated cells." (PMID 29581457, 2018). "Additionally, according to the UALCAN database, the mRNA expression levels of NEK2, NEK3, NEK4, NEK5, NEK6, and NEK8 were significantly positively correlated with the tumour grade, whereas that of NEK10 was inversely associated with this factor." (PMID 38706902, 2024). "Clinically, NEK4 mutations were significantly associated with tumor site (P=0.02), NEK9 with tobacco exposure (P=0.01), and NEK10 with improved overall survival (P=0.01)." (PMID 41716219, 2026). "We found that NEK10 was highly expressed in luminal BC tissues, significantly correlated with tumor stages, indicating a better RFS, OS, and DMFS of BC." (PMID 35368696, 2022). "Interestingly, the expression levels of NEK2, NEK6, and NEK10 were not only remarkably correlated with the tumor stage but also with the molecular subtype." (PMID 35368696, 2022). "Additionally, targeting NEK10 in cancer could disrupt oncogenic pathways and suppress tumor growth, providing a novel avenue for cancer therapy." (PMID 41154634, 2025). "Indeed, NEK10 regulatory functions might influence tumor progression by affecting the stability and activity of oncogenic proteins, making it a potential target for therapeutic intervention." (PMID 41154634, 2025). "Regardless of luminal subtype (A/B), LM cells had increased expression of ELOVL5, EFHD1, NEK10, LYPD6 and NOVA1, among others, relative to the tumor cells." (PMID 39478117, 2024).
cancer (5 papers, 2011 to 2025). A tumor composed of atypical neoplastic, often pleomorphic cells that invade other tissues. "For example, NEK10 is one of the kinases predicted to contain a driver mutation in a whole genome sequencing study of 210 primary tumors and immortalized cancer cell lines." (PMID 37046733, 2023). "This has potential implications in cancer as there has been recent research correlating Nek10 mutations and a variety of human cancers, with over 2.6% of cancers showing some Nek10 alteration." (PMID 35409400, 2022). "Since CHIP controls NEK10 stability, we explored how CHIP overexpression in cancer tissues is linked to NEK10 levels and ciliogenesis." (PMID 29581457, 2018). "Inactivating mutations of CHIP, as seen in SCAR16 disease, severely influenced cAMP-induced cilia resoprtion, whereas increased expression of CHIP was linked to reduced NEK10 levels and reduced ciliogenesis in human cancers." (PMID 29581457, 2018). "In this regard Nek10 is noteworthy in having thirteen catalogued missense mutations in six cancers." (PMID 22040655, 2011). "COSMIC analysis reveals NEK10 mutations are most present in endometrial (7.12%, n = 786), liver (10.63%, n = 2286), ovarian (7.03%, n = 967), pancreatic (7.64%, n = 2011), and skin (7.1%, n = 1786) cancers, with 21.78% of all mutations being missense substitutions." (PMID 37046733, 2023). "This highlights the importance of continuing Nek10 research and expanding scientific knowledge on its roles within cancer cells." (PMID 35409400, 2022).
NEK10 also shares sentences with these, for which no sentence is quoted: adenoma (2 papers); Abdominal obesity (1); breast tumors (1); Hypertension (1); microphthalmia (1); Obesity (1); oral cancer (1); primary ciliary dyskinesia (1).